TRPV1 (transient receptor potential cation channel subfamily V member 1)
Diseases named in the same sentence as TRPV1 in open-access papers (continued):
Sharing a sentence is not in itself a finding about the gene and the disease.
endometriosis (23 papers, 2014 to 2025). The growth of functional endometrial tissue in anatomic sites outside the uterine body. "Increased levels of TRPV1 in patients with endometriosis were positively associated with pain intensity." (PMID 37893241, 2023). "TRPV1 expression is also increased in uterosacral ligaments in endometriosis patients and it has been shown that pain is often driven by dorsal root ganglion neurons, in association with TRPV1." (PMID 34439896, 2021). "We can speculate that gut dysbiosis leads to massive influx of LPS into the blood circulation, activates TRPV1 and increases its expression, further drives peripheral nociceptor sensitization, and plays a role in endometriosis-associated pain." (PMID 38505548, 2024). "Endometriosis-associated hyperalgesia, especially local abdominal sensitivity, should be correlated with the stimuli in the peripheral nerve terminals of nociceptor neurons, such as an increase in the expression of transient receptor potential channels, TRPV1." (PMID 39192982, 2024). "Estrogen-dependent expression of TRPV1 in sensory neurons may explain why ovarian suppression can reduce endometriosis-associated pain." (PMID 25029427, 2014). "Indeed, the density of TRPV1-positive nerve fibres in ovarian endometrioma is associated with pelvic pain severity and TRPV1 mRNA is significantly upregulated in the peritoneum of women with endometriosis." (PMID 41154581, 2025). "Conversely, a significant increase in TRPV1 mRNA and protein levels was observed in rectosigmoid deep infiltrating endometriosis nodules." (PMID 41294926, 2025). "In this regard, further investigations of cytokine release and eosinophil chemotaxis after TRPV1 activation might bring new insights into the role of TRPV1 in causing itch or even pain, as an association between TRPV1 and pain has been shown, for instance, in endometriosis." (PMID 38339203, 2024). "Like other inflammatory pain diseases in which TRPV1 is correlated with pain, the expression of TRPV1 was increased at the dorsal root ganglion rats with endometriosis." (PMID 37893241, 2023). "This in turn leads to people experiencing hyperalgesia, which has been correlated with altered expression of TRPV1 in the peritoneum of people with endometriosis." (PMID 38002684, 2023). "This is not surprising, as a number of the processes responsible for TRPV1 upregulation and sensitization are found in endometriosis patients, including enhanced ROS concentrations and increased levels of neurotrophins such as NGF." (PMID 33132854, 2020). "We have previously shown that the presence of endometriosis lesions leads to increased expression of nociceptive and inflammatory markers (Trpv1, Scn11A, and Cox-2) in DRGs and spinal cords and the brains of mice with endometriosis." (PMID 31291762, 2019). "Elevated TRPV1 expression in small DRG cells innervating pelvic regions in mice with endometriosis is consistent with our previous findings that TRPV1 mRNA is elevated in peritoneal lesions from women with endometriosis." (PMID 28281561, 2017). "In women with active endometriosis, we discovered that the concentrations of mRNAs encoded by SCN11A, TRPA1, and TRPV1 were all significantly increased in the samples of peritoneum." (PMID 25029427, 2014). "TRPV1 was elevated in peritoneum (P < .01) and in lesions (P < .05) of women with endometriosis compared with the peritoneum of healthy women." (PMID 25029427, 2014). "The increased TRPV1-positive nerve fibers may integrate various stimuli on peripheral terminals or primary sensory neurons and generate hyperalgesia in endometriosis." (PMID 38505548, 2024). "It has been reported that TRPV1 is involved in endometriosis pain via ERK signalling pathway." (PMID 32613759, 2020).
endometriosis (continued). "Supporting an involvement of TRPV1 in endometriosis associated pain, elevated expression of TRPV1 has been found in dorsal root ganglion (DRG) of rats with endometriosis as well as locally on infiltrating adhesions in endometriosis patients, the increase correlating with pain intensity." (PMID 33132854, 2020). "The implication of TRPV1 in endometriosis-associated pain is clear, but the precise role of P2X3 is still under study, although there is increasing evidence of its central role in the onset of pain sensation in endometriosis." (PMID 33198179, 2020). "We only examined macrophage infiltration in the lesion on days 21 and 42, as lesion number, endometriosis-associate hyperalgesia, cytokine levels in the peritoneal cavity, and TRPV1, SP, and CGRP expression in the DRG were not altered by GATA6 deficiency until day 7 in Gata6f/f and MacGata6 KO mice." (PMID 39192982, 2024). "In summary, the results of this study indicate that therapies targeting P2RX3 may be useful in treating CPP in women with a diverse range of painful etiologies, whereas women with active endometriosis could benefit from treatments targeting TRPV1, TRPA1, SCN9A, or SCN11A." (PMID 25029427, 2014). "Formation of TRPV1/TRPA1 heteromeric calcium channels promotes the sensitization of peripheral nerve endings and enhances pain intensity in endometriosis." (PMID 39056769, 2024). "The severity of the endometriosis (including symptoms as dysmenorrhea, dyspareunia and dyschezia) correlates with exacerbated expression of TRPA1 and TRPV1 channels, suggesting that these channels play a role in this disease." (PMID 32471309, 2020). "TRPV1-immunoreactivity was increased in small, peripherin-positive, nociceptive neurons in DRG of mice with endometriosis and EP2 expression was further increased in these cells." (PMID 28281561, 2017). "We detected a significant increase in expression of EP2, COX-1 and both TRPV1 and SCN11A ion channels in the DRGs of mice with endometriosis." (PMID 28281561, 2017). "TRPV1, TRPA1, and SCN11A mRNAs were significantly higher in the peritoneum from women with endometriosis (P < .001, P < .01)." (PMID 25029427, 2014). "Recently studies have reported that TRPV1 immunoreactivity is increased in the peritoneum of women with CPP and in lesions of women with endometriosis." (PMID 25029427, 2014). "The expression of CB1, CB2 and TRPV1 has been previously reported in the endometrium and endometriotic lesions, while this study represents the first experimental evidence as regards the expression of the receptor GPR18 in endometriosis." (PMID 41294926, 2025). "Correlation identified between greater expression of TRPV1 in the peritoneum of people with endometriosis who experience CPP compared to those who do not." (PMID 38002684, 2023). "Moreover, endometrium samples from women with the most severe form of endometriosis, such as deep infiltrating endometriosis, display higher TRPA1 and TRPV1 expression than the samples from healthy women." (PMID 32471309, 2020). "They often accompany endocannabinoids in the tissues and the mRNA expression of some of the main receptors (CB1, CB2, TRPV1) in endometrial cells for women with or without endometriosis." (PMID 28861506, 2017). "TRPV1, SCN9A, and TAC1 were elevated in endometriosis lesions (P < .05)." (PMID 25029427, 2014). "Our findings are in accordance with a previous work by Sanchez and coworkers showing that CB1, CB2 and TRPV1 transcript levels were not different between endometrial stromal cells from endometriosis‐affected women and healthy controls in the proliferative phase." (PMID 41294926, 2025). "Furthermore, peritoneal biopsies from women with endometriosis display upregulation in the mRNA levels for TRPA1 and TRPV1, indicating that the pain produced in this pathology could be associated with the overexpression of these pain mediators." (PMID 32471309, 2020).
endometriosis (continued). "EP2, Cox-1, Scn11a and Trpv1 mRNA concentrations were significantly increased in dorsal root ganglia (DRG; clusters of cell bodies of afferent sensory neurons that transmit noxious stimuli from the periphery to the spinal cord) from endometriosis mice (p < 0.05); EP4 and Cox-2 were unchanged." (PMID 28281561, 2017).
fibromyalgia (23 papers, 2014 to 2026). A chronic disorder of unknown etiology characterized by pain, stiffness, and tenderness in the muscles of neck, shoulders, back, hips, arms, and legs. "In contrast, TRPV1 protein levels were augmented in fibromyalgia mice, being attenuated by 2 Hz EA, PD-L1 injection, or TRPV1 loss (yellow arrows, n = 3)." (PMID 40002809, 2025). "EA reversed these effects associated with fibromyalgia, aligning with observations in Trpv1−/− mice." (PMID 40430245, 2025). "The outcome of fibromyalgia on the TRPV1 pathway was investigated, and the linked molecular foundations of EPA were then examined." (PMID 38474148, 2024). "We found the augmented expression and localization of TRPV1 and associated kinases in a mouse model of fibromyalgia." (PMID 38474148, 2024). "The mouse mPFC is known to be involved in fibromyalgia pain through TRPV1 and the associated mediators." (PMID 38474148, 2024). "Our results indicate that EPA has an analgesic effect on fibromyalgia pain through the regulation of TRPV1 and associated molecules." (PMID 38474148, 2024). "We also implicated TRPV1 and related components in responses to fibromyalgia-like pain in the ICS model in the prefrontal cortex, somatosensory cortex, hippocampus, and thalamus of the brain." (PMID 35341159, 2022). "It would be interesting to further study whether TRPV1 is involved in cold allodynia associated with sensitive teeth and fibromyalgia affecting bones and muscles." (PMID 31831729, 2019). "We observed low PD-1 expression in the cerebellum of fibromyalgia mice but increased expression of TRPV1 and pain-related kinases." (PMID 41898229, 2026). "Our findings reveal that CB1 protein levels decreased after fibromyalgia induction, while TRPV1 and downstream kinases were increased in the key pain processing regions including DRG, SCDH, Hypo, and PAG." (PMID 40430245, 2025). "We found that hyperalgesia increased the expression of TRPV1 and related kinases in a mouse model of fibromyalgia pain." (PMID 40430245, 2025). "We also demonstrated that 2 Hz EA increased CB1 expression and decreased TRPV1 signaling in the spinal cord, contributing to alleviating fibromyalgia pain." (PMID 40430245, 2025). "This study aims to explore the role of cannabinoid receptor 1 (CB1) on transient receptor potential V1 (TRPV1) signaling pathways in a mouse model of fibromyalgia." (PMID 40430245, 2025). "pNKκB and pCREB levels were increased in the spinal cord of fibromyalgia mice but decreased with 2 Hz EA, PD-L1 injection, and Trpv1 knock out (* p < 0.05, n = 6)." (PMID 40002809, 2025). "We found decreased CB1 receptors, upregulated TRPV1, and related kinases in the dorsal root ganglion, spinal cord, hypothalamus, and periaqueductal gray in fibromyalgia mice." (PMID 40430245, 2025). "In the Hypo of fibromyalgia pain mice, we observed increased TRPV1 levels, an effect attenuated by EA and observed in Trpv1−/− mice (# p < 0.05, n = 6)." (PMID 40430245, 2025). "The chemogenetic inhibition of PVN attenuated fibromyalgia pain via the downregulation of TRPV1 pathway." (PMID 40430245, 2025). "The low TRPV1 expression in normal mice significantly increased in the SCDH of fibromyalgia pain mice (* p < 0.05, n = 6); this phenomenon was alleviated by 2 Hz EA treatment and was also observed in Trpv1−/− mice (# p < 0.05, n = 6)." (PMID 40430245, 2025). "The levels of nociceptive ion channels Nav1.7 and Nav1.8 increased after fibromyalgia induction, being decreased by 2 Hz EA, PD-L1 administration, and in Trpv1−/− mice (gray and yellow columns, * p < 0.05, n = 6)." (PMID 40002809, 2025). "Immunofluorescence staining of the dorsal root ganglion for PD-1 showed lower PD-1 expression in the dorsal root ganglion of fibromyalgia mice than in normal mice, an effect reversed by 2 Hz EA, intracerebral injection of PD-L1, or Trpv1 knock out." (PMID 40002809, 2025).
fibromyalgia (continued). "Our experiments provide evidence of necessary possessions of 2 Hz EA in mice fibromyalgia pain, especially via PD-L1/PD-1 and TRPV1 signaling pathways." (PMID 40002809, 2025). "We found that TRPV1 and related kinases were overexpressed in a mouse model of fibromyalgia pain in the dorsal root ganglion, spinal cord, thalamus, and somatosensory cortex." (PMID 40002809, 2025). "Conversely, TRPV1 levels increased after fibromyalgia induction and were decreased by EA, PD-L1 injection, or Trpv1 deletion (yellow arrows, n = 3)." (PMID 40002809, 2025). "Further, the behavioral and molecular signs of fibromyalgia were also depleted by Trpv1 gene deletion and the injection of a CB1 agonist, while the injection of a CB1 antagonist blocked the therapeutic effects of EA." (PMID 41007675, 2025). "Compared to controls, a significant increase in TRPV1, Nav1.7, and Nav1.8 levels was observed in fibromyalgia mice." (PMID 40002809, 2025). "Our data revealed that TRPV1 and related kinases were overexpressed in our mouse model of fibromyalgia pain." (PMID 40430245, 2025). "TRPV1 was presented in the dorsal root ganglion, increasing with fibromyalgia pain (133.89 ± 4.63%, red column, * p < 0.05, n = 6), while 2 Hz EA inhibited this overexpression (102.93 ± 2.57%, red column, # p < 0.05, n = 6)." (PMID 40002809, 2025). "We also demonstrated that levels of nociceptive TRPV1 and related molecules were increased after fibromyalgia induction." (PMID 40002809, 2025). "Our discoveries shed light on the involvement of CB1 in the TRPV1 signaling pathway in the effects of EA in fibromyalgia, suggesting its potential as a treatment target." (PMID 40430245, 2025). "We observed a significant decrease in CB1 expression in mice suffering from ICS-initiated fibromyalgia pain (* p < 0.05, n = 6), an effect reversed by EA or TRPV1 dysfunction (# p < 0.05, n = 6)." (PMID 40430245, 2025). "ASIC1b, ASIC3 and TRP channel subfamily V member 1 (TRPV1) were found to be the molecular determinants of acid‐induced fibromyalgia‐like pain in mice." (PMID 37417654, 2024). "Fibromyalgia mice showed higher protein levels of TRPV1 (* p < 0.05, n = 6), which EPA administration effectively decreased (# p < 0.05, n = 6)." (PMID 38474148, 2024). "Lower TRPV1 and pERK colocalizations were observed in the normal mouse mPFC compared to the fibromyalgia group." (PMID 38474148, 2024). "Fibromyalgia pain mice had significantly increased TRPV1 levels as well as increased pPKA, pPI3K, and pPKC (* p < 0.05, n = 6)." (PMID 38474148, 2024). "TRPV1 expression was potentiated in the mouse SSC after fibromyalgia pain induction (* p < 0.05, n = 6)." (PMID 38474148, 2024). "TRPV1 is significantly increased after both peripheral and central levels, such as inflammatory, fibromyalgia, and neuropathic pain models." (PMID 38339048, 2024). "TRPV1 was indicated to participate in inflammatory, fibromyalgia, and neuropathic pain and is highly expressed in small C fibers." (PMID 38339048, 2024). "In the current study, we aimed to investigate the role of TRPV1, which is the main detector and transducer of nociceptive signals, in a mice model of fibromyalgia pain." (PMID 38474148, 2024). "TRPV1 expression was significantly higher in the fibromyalgia group (* p < 0.05, n = 6), an increase attenuated by EPA treatment (# p < 0.05, n = 6)." (PMID 38474148, 2024). "The induction of fibromyalgia pain via cold stress reliably increases TRPV1 expression in the thalamus (black columns, * p < 0.05, n = 6), while EPA suppresses this effect after three intakes (black columns, # p < 0.05, n = 6)." (PMID 38474148, 2024). "The present results provide insights into the role of the TRPV1 signaling pathway for fibromyalgia and its potential as a clinical target." (PMID 38474148, 2024). "Using immunofluorescent staining, we next determined the lower expression and colocalization of TRPV1 and pERK in the normal mouse thalamus than in that of mice with fibromyalgia." (PMID 38474148, 2024).
fibromyalgia (continued). "We demonstrated that inflammatory mediators can modulate the TRPV1 signalling pathway for managing fibromyalgia pain." (PMID 35341159, 2022). "A recent article showed that the symptoms of fibromyalgia-like pain induced by ICS were improved when the TRPV1 gene was deleted (Trpv1−/−)." (PMID 35341159, 2022). "Transient receptor potential V1 (TRPV1), which is reported as a Ca2+ permeable ion channel that can be activated by inflammation, is reported to be involved in the development of fibromyalgia pain." (PMID 34082798, 2021). "We aimed to determine the therapeutic effect of EA using an effective fibromyalgia mouse model, which significantly increased the expressions of TRPV1 signaling pathway effectors in the hypothalamus, PAG, and cerebellum regions." (PMID 34082798, 2021). "We provide novel evidence that these inflammatory mediators can modulate the TRPV1 signaling pathway and suggest new potential therapeutic targets for fibromyalgia pain." (PMID 34082798, 2021). "Accumulating evidence has shown ASIC3 and TRPV1 as two major acid sensors in nociceptors that trigger acid-induced pain in mouse models of fibromyalgia." (PMID 30486810, 2018). "Overexpression of TRPV1 in the spinal cord was suppressed by acupuncture in a fibromyalgia murine model, but TRPV1 in the endothelium prevents CHD." (PMID 28245860, 2017). "Interestingly, TRPV1 increased after fibromyalgia induction compared to controls (134.21 ± 2.45%, red column, * p < 0.05, n = 6)." (PMID 40002809, 2025). "Novel chemogenetic modulation at PVN attenuated fibromyalgia pain through TRPV1 pathway." (PMID 40430245, 2025). "We induced fibromyalgia pain in normal and Trpv1−/− mice through ICS induction." (PMID 40002809, 2025). "TRPV1 activation cooperates with protein kinase A (PKA), phosphoinositide 3-kinase (PI3K), and PKC in the modulation of pain, indicating its crucial role in central sensitization linked with fibromyalgia pain at both peripheral and central nervous systems." (PMID 40430245, 2025). "In contrast, levels of pain-related kinases increased after fibromyalgia induction, an effect which could be reversed by EA, PD-L1, or Trpv1 deletion." (PMID 40002809, 2025). "Initially, we aimed to determine whether PD1 and TRPV1 affect fibromyalgia pain in peripheral dorsal root ganglion areas." (PMID 40002809, 2025). "ICS-induced fibromyalgia resulted in mechanical and thermal pain, as indicated by von Frey and Hargreaves tests on mice, an effect that can be reversed with 2 Hz EA, PD-L1 injection, or Trpv1 deletion." (PMID 40002809, 2025). "Similarly to other tissues, levels of TRPV1-associated kinases such as pPKA, pPI3K, and pPKC all increased after ICS-induced fibromyalgia; these effects were alleviated by EA and in Trpv1−/− mice (# p < 0.05, n = 6)." (PMID 40430245, 2025). "Additionally, chemogenetic regulation at the PVN reliably modulated fibromyalgia pain through the TRPV1 pathway." (PMID 40430245, 2025). "In addition, fibromyalgia pain increased TRPV1 expression, while 2 Hz EA significantly suppressed such overexpression after two sessions." (PMID 40430245, 2025). "Similarly, pPI3K, pAkt, and pmTOR expression increased in fibromyalgia mice compared to normal mice, becoming significantly decreased by 2 Hz EA, intracerebral injection of PD-L1, and Trpv1 deletion." (PMID 40002809, 2025). "Since the precise mechanisms behind the effects and mechanisms of EPA in this model remain unknown, we evaluated EPA in the expression of the TRPV1 signaling pathway in a murine fibromyalgia pain model." (PMID 38474148, 2024). "Therefore, it is very important to study the mechanisms of TRPV1 in fibromyalgia pain, especially to explore its molecular mechanisms in the brain." (PMID 38474148, 2024). "In addition, we recently showed that EA reliably attenuates either mechanical or thermal hyperalgesia in fibromyalgia mouse models by inhibiting the TRPV1 pathway." (PMID 38339048, 2024).